MSH6 (mutS homolog 6)
Diseases named in the same sentence as MSH6 in open-access papers (continued):
Sharing a sentence is not in itself a finding about the gene and the disease.
Lynch syndrome (continued). "Of the five individuals with germline:somatic alteration of a L-MMR gene, four carried a germline LOF variant that is known to be pathogenic for Lynch syndrome, and one carried a LOF variant MSH6 (p.I855fs) not present in ClinVar." (PMID 30217226, 2018). "The patient also has a diagnosis of Lynch syndrome, known as hereditary nonpolyposis colorectal cancer (HNPCC), due to the presence of one mutated allele of MutS Homolog 6 (MSH6) (MSH6p.T716fs) on his genetic testing results." (PMID 29946497, 2018). "The MSH6 participants included in this study are representative of all the HNPCC patients tested in New South Wales, Australia from 1997 to 2008, which we estimate is approximately half of the Australian HNPCC/Lynch syndrome families." (PMID 20487569, 2010).
Lynch syndrome (continued). "It should also be noted that the majority of our patients carried MSH6 and PMS2 variants and thus may not be representative of all Lynch syndrome cohorts." (PMID 37078003, 2022). "The very high population frequencies of variants in MSH6 and PMS2 without typical Lynch syndrome associated cancers may ironically have falsely elevated the odds ratio." (PMID 34439310, 2021).
Lynch syndrome (continued). "Using IHC with a two-antibody (MSH6 and PMS2) panel would (assuming that no Lynch syndrome cases were missed) save approximately £15 per patient compared to using the full panel with no change in QALYs." (PMID 32492863, 2020).
colorectal cancer (206 papers, 2004 to 2026). A primary or metastatic malignant neoplasm that affects the colon or rectum. "A study on colorectal cancer subjects treated with a FOLFOX4 regimen observed an association of the MSH6 557G > T polymorphism with neutropenia." (PMID 39003369, 2024). "Single mutations were identified in MEN1 for gastric cancer, MSH6 for colorectal cancer, CDKN2A for pancreatic cancer, and EPCAM/TSC2/GALNT12 for breast cancer." (PMID 38201513, 2023). "MSH6 mutations are associated generally with endometrial cancer and increase the likelihood of colorectal cancer by eightfold." (PMID 37658412, 2023). "MMR deficient MSH6 mutant DLD-1 human colorectal cancer cells with a high spontaneous mutation rate and a typical MMRd mutation spectrum and MMR proficient TK6 human lymphoblastoma cells with a low mutation rate were chosen for the study." (PMID 37791890, 2023). "His colorectal cancer contained tumor-specific frameshift mutation in MSH6 and as many as 1251 nonsynonymous mutations." (PMID 35228610, 2022). "Some of these sites were reported to be mutated in familial colorectal cancer patients with germline MSH6 mutations and characterized by a low microsatellite instability phenotype." (PMID 36189922, 2022). "We present the first report of a CMMRD patient with a de novo variant in MSH6, who developed colorectal cancer in childhood." (PMID 33568103, 2021). "Here we report a case of CMMRD with compound heterozygous variants in the MSH6 gene, including a de novo variant in multiple colorectal cancers." (PMID 33568103, 2021). "This phenomenon is compatible with the previous literature, that demonstrated the reduced expression of MSH6 in a somatic mutation manner, in colorectal carcinomas of MLH1/PMS2-deficient type of LS." (PMID 32611331, 2020).
colorectal cancer (continued). "In recent years, a two-antibody panel approach using PMS2 and MSH6 was proposed as an effective screening protocol for colorectal carcinoma with mismatch repair protein deficiency." (PMID 28451866, 2018). "Mutations in MSH6 have been suggested to affect families with atypical LS, which manifests as a late onset of disease, lower incidence of colorectal cancer and a high incidence of endometrial cancer." (PMID 26437257, 2015). "The remained case was a MSI-H glioblastoma with loss of MSH6 expression and a family history of colorectal cancer." (PMID 24073290, 2013). "EPCAM deletion carriers will probably be more easily recognized than carriers of an MSH6 mutation, whose colorectal cancer risk is lower with a higher age of onset." (PMID 23938213, 2013). "Of the total 78 MSH6 mutation positive participants belonging to 29 families, only 21 participants (27%) had developed colorectal cancer (CRC)." (PMID 20487569, 2010). "The MSH6, c.3202 C > T mutation, located on exon 5 of the gene, has been identified in an individual diagnosed with colorectal cancer at the age of 40." (PMID 20937110, 2010). "These in turn represent 2–7% of all colorectal cancers, indicating that germline mutations in MSH6 account for ∼0.3% of cases." (PMID 21081928, 2010). "TGFBR2, MSH3 and MSH6 microsatellite sequences present high mutational rates in right MSI-H colorectal cancer, demonstrating that alterations in these genes are important for the development of MSI neoplasias." (PMID 20979647, 2010). "Our findings suggest that germline MSH6 mutations contribute to a subset of early-onset colorectal cancer." (PMID 16940983, 2006). "Further studies are warranted to understand the genetic and environmental factors responsible for the variable penetration of MSH6 germline mutations, as well as to identify other causes of early-onset colorectal cancer." (PMID 16940983, 2006). "To assess their significance we studied five novel MSH6 missense mutations in six patients derived from a series of consecutive endometrial and colorectal cancer patients selected for study after their tumours were determined to be microsatellite unstable." (PMID 15354210, 2004). "c.3261dupC is a PV in the MSH6 gene, a duplication responsible primarily for colorectal cancer risk, while the c.2136delG variant is a frameshift mutation cited in the literature as also being associated with BC, but apparently without related microsatellite instability." (PMID 40508121, 2025). "Thus, understanding of microsatellite instability (MSI) detection in colorectal carcinomas (CRCs) using immune histochemical markers MSH6 and PMS2, improving diagnostic and prognostic approaches for CRC." (PMID 41907888, 2025). "PVs in MSH6 confer a high risk of endometrial cancer but modest risk of colorectal cancer." (PMID 38356732, 2024).